CXCL12 (C-X-C motif chemokine ligand 12)
Diseases named in the same sentence as CXCL12 in open-access papers (continued):
Sharing a sentence is not in itself a finding about the gene and the disease.
cancer (continued). "For example, in malignant tumors, cancer-associated fibroblasts (CAFs) serve as the main source of inflammatory factors including CXCL12, CXCL1, and IL-6, and participate in the regulation of immune responses in various malignant tumors (e.g., pancreatic ductal adenocarcinoma)." (PMID 35967331, 2022). "Studies indicate that FAP+ TAFs produce CXCL12/SDF-1 that may be responsible for coating cancer cells and causing T-cell exclusion." (PMID 35814453, 2022). "The remarkably specific association of CXCL12 with KRT19 on cancer cells in human and mouse tumors and on human cancer cell lines may be a consequence of the manner in which the CXCL12–KRT19 coating is formed." (PMID 35046049, 2022). "Cancer cells acquire resistance to chemotherapy through the emergence of genetic mutations or epigenetic changes, favoring the activation of signaling pathways related to chemotaxis, cell survival or proliferation, including the CXCL12/CXCR4 axis." (PMID 35532120, 2022). "On the other hand, it will be interesting to test whether miR-455-5p/CXCL12 interaction is implicated in other diseases or cancers in the future." (PMID 33962657, 2021). "Stromal cells, especially cancer-associated fibroblasts (CAFs), are the main producers of CXCL12." (PMID 33859752, 2021). "Combined, these results argue against a possibility that cancer progression could be affected by indirect effects of stromal CXCL12 loss on mouse energy balance." (PMID 33753872, 2021). "Likewise, cancer-associated fibroblasts (CAFs)-derived CXCL12 attracts monocytes with the M2 like phenotype and induces their transformation into M2 macrophages in oral squamous cell carcinoma." (PMID 33096815, 2020). "In addition to the biological effects mediated by CXCL12 axis, investigations are also conducted associated with the transcriptional regulation of CXCL12 axis during cancer progression." (PMID 33363463, 2020). "CXCL12 is also found to be closely associated with onset and development of human cancer." (PMID 32519739, 2020). "CXCL12 expression is also associated with the survival of cancer patients, but the role is dual." (PMID 32641130, 2020). "Although the molecular mechanisms underlying cancer metastasis remain to be fully elucidated, accumulating evidence points on a significant role of CXCL12/CXCR4 in the process, suggesting that the CXCL12/CXCR4 axis may be a potential therapeutic target in BC." (PMID 32228629, 2020). "T cell exclusion may also be mediated by cancer-associated fibroblasts, which produce the C-X-C motif chemokine 12 (CXCL12)." (PMID 32423420, 2020). "CXCL12 secreted by cancer-associated fibroblasts promotes the proliferation of breast tumor cells." (PMID 31398937, 2019). "The level of serum CXCL12 is associated with a high mortality rate in cancer patients." (PMID 31398937, 2019). "Although stromal-derived CXCL12 is implicated in the growth of several cancers, it may also be involved in dormancy." (PMID 29642534, 2018). "Cells expressing strongly CXCL12 in the stromal niche are mostly endothelial cells and perivascular mesenchymal stromal cell populations including cancer-associated fibroblasts, and CXCL12 levels are variably modulated in response to local or remote pro-inflammatory stimuli." (PMID 28423491, 2017). "Moreover, genes encoding CAF secretory factors that promote cancer cell invasion and disease progression, including CXCL12, TGFβ1, and PDGFα, were upregulated in CSC-derived fibroblasts." (PMID 28754894, 2017). "Many cell types in tumors secrete CXCL12, most notably cancer-associated fibroblasts." (PMID 29117251, 2017). "Thus, this study demonstrated, for the first time, an association between FOXP3 and CXCL12 genetic polymorphisms with this cancer, demonstrating that these markers are, somehow, involved in WT pathogenesis." (PMID 27830498, 2016). "This further supports the hypothesis that dysfunction of the CXCL12/CXCR4 signaling pathway contribute to the pathogenesis of HPV-associated cancer." (PMID 27918748, 2016).
cancer (continued). "The CXCL12/CXCR4/CXCR7 signaling axis is highly implicated in metastasis of many cancers." (PMID 25909600, 2015). "Furthermore, overexpression of CXCL12 is associated with the development and metastasis of many kinds of cancers." (PMID 25268356, 2014). "A significant association between CXCL12 G801A polymorphism and cancer risk was found under an additive genetic model (OR = 1.30, 95% CI = 1.16–1.45), a dominant genetic model (OR = 1.37, 95%CI = 1.19–1.58), and a recessive genetic model (OR = 1.38, 95% CI = 1.13–1.69)." (PMID 25268356, 2014). "In the subgroup analysis by ethnicity, the CXCL12 G801A polymorphism was found to confer an increased cancer risk among Asians under all the genetic models, whereas in the Caucasian subgroup, a significant association was only observed under an additive genetic model and a dominant genetic model." (PMID 25268356, 2014). "The CXCL12 G801A polymorphism has been investigated in various types of cancers." (PMID 25268356, 2014). "Pooled ORs and 95% CIs of the association between CXCL12 G801A polymorphism and cancer risk." (PMID 25268356, 2014). "In addition, the sample size of each study is relatively small; thus, their statistical power is too low to detect associations between the CXCL12 G801A polymorphism and cancer risk." (PMID 25268356, 2014). "However, the results of previous studies conflicted about the association between CXCL12 G801A polymorphism and cancer risk." (PMID 25268356, 2014). "The CXCL12/CXCR4 signaling axis has been implicated in both cancer metastases and HIV-1 infection." (PMID 23202899, 2012). "CXCL12/CXCR4 signaling has become increasingly implicated with various human cancers." (PMID 21949786, 2011). "Since CXCR4 and CXCL12 are implicated in theprogression of many different cancers, it is of interest to determine whetherDIM and/or genistein downregulate these proteins in cancer cell lines of otherorigins." (PMID 19325924, 2009). "Additionally, cancer-associated fibroblasts (CAFs) formed CXCL12-mediated immune exclusion zones." (PMID 40819059, 2025). "Thus, blocking CXCL12 or MAPK may prevent the effects of CXCL12 / CXCR4 axis hence reversing the persistent pain associated with cancer." (PMID 39641645, 2024). "In addition, compared with untreated tumors, tumors treated with SGT-53 showed increased mRNA expression of chemokines including Cxcl9, Cxcl10, and Cxcl12, which are associated with increased infiltration of activated T cells in various human cancers via the chemokine receptors CXCR3 and CXCR4." (PMID 36359830, 2022). "Additionally, CSCs and endothelial cells combined within the tumor microenvironment can transform normal fibroblasts into cancer-associated fibroblasts (CAFs) possessing increased proliferation and secreting unique cytokines, such as CXCL12, VEGF, PDGF and HGF." (PMID 30510501, 2018). "Moreover, the CXCR4/CXCL12 axis seems to be tightly linked to the immune checkpoint regulator programmed death 1 (PD-1) and programmed death-ligand 1 (PD-L1) that co-operate to suppress anti-cancer immunity." (PMID 27462860, 2016). "The relatively poor response in immunotherapy efficacy of PDACs might be related to specific carcinoma-associated fibroblasts (expressing fibroblast activation protein), which secrete C-X-C motif ligand 12 (CXCL12) and thus stop T cells from accessing cancer cell regions in the stroma." (PMID 27655706, 2016). "In addition, gene-gene and gene-environment interactions may influence the association between CXCL12 G801A polymorphism and susceptibility to specific cancers." (PMID 25268356, 2014). "Moreover, coculture of cancer stem cells with pancreatic stromal cells which express CXCL12 was associated with an increased migration and invasion ability of cancer stem cells, and these effects were significantly reduced by CXCR4 downregulation using RNA interference." (PMID 24212636, 2011).
cancer (continued). "Our analysis revealed 9 shared genes, with UBE2C, POLQ, RAD51, and HOXB7 being up-regulated and EDNRB, GPD1L, F10, SORBS2, and CXCL12 down-regulated in both cancers." (PMID 41790655, 2026). "For instance, increased CXCL12 in rat mammary adenocarcinoma cells led to higher micro-vessel density and enhanced cancer cell invasiveness." (PMID 40211853, 2026). "Analysis of a single cell RNA‐seq database derived from human cancer patients revealed that CXCL12 was predominantly expressed in CAFs." (PMID 41257391, 2026). "The activation of CXCR4 and the migration of cancer cells towards organs that express CXCL12 facilitate the directed metastasis of cancer cells." (PMID 40923371, 2025). "Subsequently, assessing the relationship between CXCL12 expression and immune presence in cancer utilizing GEPIA and TIMER." (PMID 40166682, 2025). "Lastly, a correlation study was performed examining CXCL12 expression and immune cell infiltration in multiple cancer types." (PMID 40166682, 2025). "Similar inhibition of CXCL12-induced cell migration by the EPI-X4 derivative was recently reported in migrating cancer cells." (PMID 41331944, 2025). "CAF-derived cytokines, including IL-6, GM-CSF, and CXCL12, induced the differentiation and activation of myeloid-derived suppressor cells (MDSCs) and TAMs to favor cancer progression." (PMID 40447617, 2025). "Cancer cells interact with the bone marrow stroma via signaling molecules such as CXCL12/CXCR4, and by doing so they can occupy the bone marrow niche of hematopoietic stem cells, and then proliferate or become dormant." (PMID 40224177, 2025). "The F_6 CCL19+ fibroblasts have been shown to interact with T-cells via CXCL12/CXCR4 and F_8 MMP1+ myofibroblasts (myoF) have recently been linked to an immunosuppressive neighborhood in cancer." (PMID 41438752, 2025). "Utilizing TIMER, CIBERSORT, CIBERSORT-ABS, QUANTISEQ, XCELL, MCPCOUNTER, and EPIC algorithms, we examined the potential link between CXCL12 expression and immune cell infiltration in various TCGA cancer types." (PMID 40166682, 2025). "Again, the CXCR4/CXCL12 axis promotes chemo-resistance, and chemotherapy can upregulate CXCR4/CXCL12 expression in multiple forms of cancer." (PMID 40142155, 2025). "The study also proposes disrupting the heterocomplex as a potential therapeutic target to inhibit cancer invasion and metastasis, emphasizing the important roles of CXCL12 and CXCR4 in this process." (PMID 41347146, 2025). "This suggests a directional migration mechanism in which high CXCL12 concentrations in lymph nodes attract CXCR4-expressing cancer cells, thereby facilitating lymphatic spread." (PMID 41149503, 2025). "Cancer cells induce a TGF-β-dependent increase in CXCR4 levels in monocytes, and CXCL12 expressed by perivascular fibroblasts attracts these mobile TAMs to blood vessels, entrapping mobile cancer cells." (PMID 40427136, 2025). "In fact, CXCL12 expression levels are increased at sites of metastasis such as the brain, bone marrow, lung, and liver, so cancer cells can exploit the CXCR4/CXCL12 axis to establish distant organ metastasis." (PMID 40142155, 2025). "Other features of the CXCR4/CXCL12 signalling pathway include being a contributor to drug resistance by enriching the cancer stem cells (CSCs) and creating an immunosuppressive surrounding microenvironment." (PMID 41002447, 2025). "Pathways activated by CXCL12, predominantly in cancer cells, include EMT, hormone ER, PI3K/AKT, RAS/MAPK, RTK, and TSC/mTOR." (PMID 40166682, 2025). "In neuroblastoma, SOX17 inhibited cancer cell proliferation and invasion through the CXCL12/CXCR4 signaling axis." (PMID 40909292, 2025). "Mechanistically, CYP4X1/sEH-derived 14,15-EET-EA upregulates PD-L1, CXCL12, and TGF-β in cancer-associated fibroblasts (CAFs) via the GPR119-Gs/β-arrestin 2 signaling axis." (PMID 41276938, 2025). "CAF-derived CXCL12 promotes cancer cell growth, invasion, and stemness by altering cell motility and increasing vascular permeability." (PMID 40230452, 2025).
cancer (continued). "In the stromal compartment, phosphorylation of PCNA at Y211 in fibroblasts drives secretion of cytokines such as transforming growth factor beta (TGFβ) and C-X-C motif chemokine ligand 12 (CXCL12), which enhance cancer stemness and invasion potential." (PMID 41170373, 2025). "CXCR4+ cancer cells easily migrate where CXCL12 is highly expressed, towards organs such as the lungs, lymph nodes, and bones, which represent the most common metastasis sites." (PMID 40142155, 2025). "This shows that CXCL12 retains T cells in the stroma and limits their access to cancer cells, thereby impairing antitumor immunity and potentially contributing to poor prognosis." (PMID 40849508, 2025). "Results indicated a significant positive correlation between CXCL12 and most immune cells across 33 cancers, notably SKCM, KICH, UVM." (PMID 40166682, 2025). "The CXCR4/CXCL12 axis is heavily connected to cancer metastasis, as it is involved in several steps: adhesion, invasion, cell proliferation, and survival." (PMID 40142155, 2025). "Inhibition of CXCL12 resulted in T-cell accumulation and acted synergistically with PD-L1, thereby diminishing the growth of cancer cells." (PMID 40427098, 2025). "CQ has been shown to inhibit the TLR9/nuclear factor kappa B signaling pathway, thereby reducing cancer invasiveness, and both CQ and HCQ can suppress cancer cell proliferation by interfering with the CXCL12/CXCR4 signaling pathway." (PMID 40805187, 2025). "CXCR4 has a unique ligand known as CXCL12 (also known as stromal-derived factor-1 or SDF-1), which is secreted from multiple stromal components in the TME, such as cancer-associated fibroblasts (CAFs), mesenchymal stem cells and endothelial cells." (PMID 41002447, 2025). "Occasionally, cancer cells produce CXCL12; more commonly, they foster an environment involving paracrine signaling and cytokines to stimulate CXCL12 production by stromal cells." (PMID 40485724, 2025). "The results suggest that for BLCA’s 33 cancers, CXCL12 acts as a significant risk factor for DSS.The result found that high CXCL12 groups have statistically better OS than those for the low CXCL12 groups in CCSK, LUAD, LIHC, LARC, CESE." (PMID 40166682, 2025). "In bladder cancer, senescent CAFs secreting CXCL12 can promote cancer progression in mice and humans." (PMID 40862837, 2025). "Monoclonal antibodies (mAbs) targeting CXCR4 have shown promising results in both solid tumors and hematological malignancies by blocking the CXCR4/CXCL12 axis and inducing cancer apoptosis." (PMID 40307933, 2025). "The CXCL12/CXCR4 axis has been implicated in the regulation of cancer cell proliferation, invasion, angiogenesis, and metastasis in several types of cancers, including GC." (PMID 40481962, 2025). "A key finding is the synergistic effect of GPR15LG with CXCL12, enhancing CXCL12-mediated migration and signaling in both, immune and cancer cells." (PMID 40394646, 2025). "Considering the increasing relevance of the CXCR4/CXCL12 axis in cancer, several effective antagonists have been discovered in the last few years, most of them using AMD3100 as a lead compound." (PMID 40142155, 2025). "In contrast, the CXCL12/CXCR4 axis, widely implicated across multiple cancer types, drives PI3K/AKT and PI3K/AKT/mTOR signaling, macrophage recruitment, and metastatic spread, particularly to the liver." (PMID 40943634, 2025). "Despite extensive investigation, the precise pathophysiology remains elusive.This article explores new autophagy-related DEG genes between EM and EAOC, and investigates CXCL12’s expression and prognostic relevance across pan-cancer." (PMID 40166682, 2025). "The CXCL12/CXCR4 axis is particularly significant in PDAC,as CXCR4 is overexpressed in cancer cells while its ligand, CXCL12, is upregulated in dorsal root ganglia (DRG)." (PMID 40981722, 2025).
cancer (continued). "Bidirectional communication between cancer stem cells (CSCs) and cancer-associated fibroblasts (CAFs) amplifies stemness via paracrine stimulation of the IL-6/STAT3, TGF-β/SMAD, and CXCL12/CXCR4 signaling pathways." (PMID 41439922, 2025). "Serum CXCL12 concentrations were also evaluated in healthy dogs and in 24 dogs with epithelial malignant tumors." (PMID 40849508, 2025). "Collectively, these findings underscore the role of the CXCL12 axis in mediating cancer chemoresistance." (PMID 38818409, 2024). "In previous studies, abnormal CXCR4/CXCL12 signaling was involved in a variety of pathophysiological processes, such as cancer and organismal inflammation." (PMID 39026682, 2024). "On the contrary, cancer cells with low metastatic potential, lack thioredoxin reductase, promptly uptake CXCL12 and fail to respond to the heterocomplex." (PMID 38803493, 2024). "The immunohistochemical analysis revealed significantly higher expression of CD44, MYC, IL17A, CXCL1, FCGR3A, SPP1, and IL1A in cancer tissues, while CXCL12 and CCL5 showed significantly higher expression in adjacent normal tissues." (PMID 39767563, 2024). "Chemokines like CXCL12 help maintain localized niches of cancer stem cells (CSCs) which have immunosuppressive effects through factors like IL-10 and TGF-β, leading to therapy resistance." (PMID 39076974, 2024). "The CXCL12/CXCR4 axis plays an important role in various aspects of cancer biology, including angiogenesis and metastasis." (PMID 39641645, 2024). "Peptide E5-modified CdSe/ZnS QDs significantly enhanced the binding affinity to CXCL4-overexpressing cancer cells and inhibited the CXCL12-induced migration of cancer cells." (PMID 38998693, 2024). "The CXCL12/CXCR4 pathway in cancer promotes metastasis but the molecular details of how this pathway cross-talks with oncogenes are understudied." (PMID 39766093, 2024). "These fibroblast-like cells were permissive for de novo KSHV infection, and one lineage produced CXCL12, a cancer-promoting chemokine." (PMID 39386738, 2024). "CXCL12, secreted by stromal cells, is known to attract cancer cells by stimulating the CXCR4 receptor, which is upregulated in lung tumor cells." (PMID 39771496, 2024). "The impact of the CXCL12/CXCR4 axis on promoting GBM growth has spurred the development of effective CXCR4 antagonists as potential anti-cancer drugs." (PMID 39162901, 2024). "This overexpression would naturally capture CXCL12 at the surface of cancer cells, an effect that would distort the gradient that attracts typically immune cells to tumors." (PMID 39511139, 2024). "CXCR7 agonists can be alternative choices but with the diverse roles of CXCR7 have been reported, ranging from compensating for CXCR4 inhibitors, promoting cancer progression, treatment failure, and to counteracting CXCL12 function." (PMID 38898023, 2024). "Therefore, we speculate that targeted inhibition of CXCL12 may alleviate cancer-associated pain." (PMID 39641645, 2024). "In animal models of cancer pain, the CXCL12 / CXCR4 axis has been found to mediate the effects of astrocytes on cancer-associated pain." (PMID 39641645, 2024). "Activation of the CXCL12/CXCR4 biological axis plays an essential role in the pathophysiology of several cancer types, including progression, recurrence, and metastasis." (PMID 38594611, 2024). "Elevated release of CXCL12 in prevalent metastatic sites can draw cancer cells and enhance their migration to these locations." (PMID 39771496, 2024). "An integrative meta-analysis study has revealed that miR-140 downregulated CXCL12 expression to be involved in muscular atrophy during cancer cachexia." (PMID 39404384, 2024). "CXCL12/CXCR4 is a key signaling pathway that recruits TAMs, and the blockade of the CXCL12/CXCR4 possesses great potential for cancer treatment." (PMID 38787372, 2024).